RNU6-1326P (RNA, U6 small nuclear 1326, pseudogene)
Gene: Small nuclear RNA gene on chromosome 21 (15,614,283 to 15,614,389, forward strand). Ensembl gene ENSG00000212564.
Homologues: Orthologues: chimpanzee U6 (95% identical), macaque U6 (91% identical), guinea pig U6 (76% identical), pig U6 (74% identical), rabbit U6 (72% identical), mouse Gm26424 (64% identical). Paralogues in human: RNU6-698P (82% identical), RNU6-831P (82% identical), RNU6-199P (81% identical), RNU6-236P (81% identical), RNU6-891P (81% identical), RNU6-1042P (80% identical), RNU6-116P (80% identical), RNU6-1175P (80% identical), RNU6-1252P (80% identical), RNU6-188P (80% identical), RNU6-211P (80% identical), RNU6-47P (80% identical), and 1287 more.